IGF2BP3 (insulin like growth factor 2 mRNA binding protein 3)
Diseases named in the same sentence as IGF2BP3 in open-access papers (continued):
Sharing a sentence is not in itself a finding about the gene and the disease.
cancer (continued). "IGF2BP3, one of the readers of m6A methylation, has been shown to play a regulatory role in many diseases including cancer and cardiovascular diseases; however, its role in RA is unknown." (PMID 35479077, 2022). "Elevated levels of IGF2BP3 expression are correlated with diminished patient survival in many cancers and may be a marker of disease aggressiveness in B-ALL." (PMID 34321607, 2022). "Furthermore, a wound healing assay was carried out to discover what influence IGF2BP3 reduction had on cancer cells' metastatic ability." (PMID 34647424, 2022). "In addition, with increasing IGF2BP3 expression, the cancer-promoting signalling pathways were significantly enriched in the TCGA and CGGA datasets, as estimated via the ssGSEA algorithm, which is consistent with the enrichment analysis of circNEIL3." (PMID 35031058, 2022). "In addition, the Oncomine database was used to verify the high expression of IGF2BP2 and IGF2BP3 in cancer tissues." (PMID 36686749, 2022). "Interestingly, the expression of IGF2BP1 and IGF2BP3 increased more than twofold in most cancer types." (PMID 35794212, 2022). "For example, the level of IGF2BP3 overexpression correlates with cancer progression and survival." (PMID 35833147, 2022). "Accumulating evidence indicates that IGF2BP3 plays a tumour‐promoting role in human cancers." (PMID 34894048, 2022). "Moreover, functional enrichment analysis suggested that differentially expressed genes (DEGs) of groups with high versus low IGF2BP3 expression were related to immune- and cancer-related pathways." (PMID 35677634, 2022). "Moreover, IGF2BP3 played significant roles in cell proliferation, migration, and adhesion during cancer progression, and it has been recognized as an indicator for cancer progression and metastasis and a predictor of poor prognosis for many types of cancers." (PMID 35565448, 2022). "IGF2BP3 functions as a RNA binding protein and is involved in various cancer-related processes." (PMID 37305324, 2022). "Whether circRNAs and IGF2BP3 interact in cancer or even under homeostatic conditions is largely unknown." (PMID 35986300, 2022). "Furthermore, the nomogram showed the role of IGF2BP3 and other clinicopathological characteristics in predicting cancer metastasis in NPC patients after initial treatment." (PMID 34894048, 2022). "IGF2BP3 is a highly conserved paralog of IGF2BPs and primarily exerts oncogenic effects in cancer." (PMID 35401168, 2022). "The role of METTL14 and IGF2BP3 in human cancers was studied before." (PMID 33718187, 2021). "IGF2BP3 primarily plays an oncogenic role in various cancers." (PMID 33917399, 2021). "For example, YTHDF1 and IGF2BP3 were up-regulated in 11 cancer types except for THCA." (PMID 33718187, 2021). "IGF2BP3 is an oncogenic protein that is overexpressed in many human cancers." (PMID 35127504, 2021). "In addition, we found that IGF2BP3 is one of the two m6A regulatory factors with the most significant correlation with metastasis-related genes in the GEO carcinoma in situ data set." (PMID 34737950, 2021). "Moreover, multiple evidences proved that IGF2BP3 is relate to the processes of cancer development and prognosis." (PMID 32984260, 2020). "The other 6 putative CPAs demonstrated diverse expression profiles, ranging from those found only in a restricted set of cancer types (IGF2BP3, ADAM12), to those overexpressed in most cancer types but also demonstrating elevated expression in normal female reproductive tissues (CAPN6, MMP11)." (PMID 33087697, 2020). "A growing body of evidence shows that IGF2BP3 has shown its promising value on cancer therapy." (PMID 32984260, 2020). "A previous study reported IGF2BP3 overexpression in a variety of types of human cancers." (PMID 33297932, 2020). "It has been established that insulin‐like growth factor 2 mRNA‐binding protein 3 (IGF2BP3) is a RNA binding protein (RBP) that functions in cancers, therefore, we hypothesized that IGF2BP3 may bind to CERS6‐AS1 in BC cells." (PMID 31701672, 2020).
cancer (continued). "Abundant evidence has clarified that the expression of IGF2BP3 could enhance the invasive potential of malignant cells and correlate with poor outcomes and progressive metastases in human cancers." (PMID 32760394, 2020). "In other types of human carcinoma, IGF2BP3 was also a valuable prognosis marker." (PMID 32710725, 2020). "In lung adenocarcinoma, overexpression of IGF2BP3 may induce the proliferation of cancer cells by mRNA degradation." (PMID 32083017, 2019). "Recently, IGF2BP3 has been identified as a potential oncogene across multiple cancer types." (PMID 32047515, 2019). "Moreover, m6A regulators were found to be potentially useful for prognostic stratification, and we identified IGF2BP3 as a potential oncogene across multiple cancer types." (PMID 31521193, 2019). "The percentage of apoptotic cancer cells was enhanced by both IGF2BP3 siRNAs." (PMID 32083017, 2019). "IGF2BP3 functions as a potential oncogene across multiple cancer types." (PMID 31801551, 2019). "From the results of GSEA (Gene Set Enrichment Analysis) in a published GC cohort NCBI/GEO/GSE62254 (n = 300), IGF2BP3 upregulation was found to have a positive correlation with expression of a common cancer gene set which was defined by a group of Singaporean researchers (P < 0.001)." (PMID 28399871, 2017). "We propose that the transcriptional and posttranslational modulation may work together for IGF2BP3 to function as a potential oncogene in cancer development." (PMID 29212181, 2017). "IGF2BP3 may increase the cancer stem cell percentage through IGF2 in HCC, which probably lead to the stemness-related genes like CD133 and ABCB1 expression up-regulation." (PMID 26327240, 2015). "In mice injected with control-RNAi S2-013 cells, the surface of the peritoneum was covered with a relatively thick layer of cancer cells, and cancer cells invaded muscular tunics; however, in mice injected with IGF2BP3-RNAi cells, large areas of peritoneum were free of cancer cells (data not shown)." (PMID 25216519, 2014). "Overexpression of IGF2BP3 has been reported in several cancer types." (PMID 23688189, 2013). "IGF2BP1 and IGF2BP3 have been found to be re-expressed in several aggressive cancer types." (PMID 23069990, 2013). "Additionally, although many studies have highlighted the importance of lncRNAs in mediating the stability of IGF2BP3 targets in cancer, it is unclear whether lncRNAs collaborate with IGF2BP3 to regulate ferroptosis‐related targets." (PMID 40391780, 2025). "In this section, we wonder whether IGF2BP3 plays an important role in pan-cancer." (PMID 38577615, 2024). "Thus, as a new molecular marker, IGF2BP3 could become a potential therapeutic target for cancer treatment." (PMID 37877353, 2023). "IGF2BP3 may also have the potential as a therapeutic target for cancer treatment." (PMID 36761737, 2023). "The data indicated that IGF2BP3 might be associated with chemoresistance of specific chemotherapeutic agents, such as Trametinib, Cobimetinib, ARRY-162 and Selumetinib, which were commonly used MEK inhibitors approved by the FDA for cancer therapy." (PMID 36761737, 2023). "Thus, we recognized that IGF2BP3 is an oncofetal protein, and IGF2BP3 may be an emerging cancer biomarker." (PMID 37859812, 2023). "Therefore, a positive feedback loop may exist between the EGFR/MEK/MAPK pathway and IGF2BP3 expression in cancer cells." (PMID 37658049, 2023). "Based on our findings, IGF2BP3 may serve as a biomarker for the clinical detection of cancer." (PMID 36761737, 2023). "In addition, targeting IGF2BP1 and IGF2BP3 could be more specific for tumors and safer for patients, given their absence in normal tissues and high levels in many cancers." (PMID 37280679, 2023). "However, IGF2BP3 overexpression is noted in a wide range of cancer types—with different oncogenic transcriptional programs—and further work is needed to define whether this paradigm may be operant in other hematologic and nonhematologic cancer." (PMID 34321607, 2022).
cancer (continued). "Moreover, we also discovered several ICD-related therapeutic targets including IGF2BP3 which might benefit cancer patients who could hardly respond to immunotherapy." (PMID 36497433, 2022). "Therefore, a positive feedback loop may exist between the IGF/PI3K/MAPK/mTOR pathway and IGF2BP3 expression in cancer cells." (PMID 32010687, 2019). "Thus, control of the expression of IGF2BP3 may be a potential therapeutic target for cancer control." (PMID 29212181, 2017). "IGF2BP3 is an RNA-binding protein that is upregulated in ovarian clear cell carcinoma (OCCC) and promotes cancer cell proliferation and tumour formation." (PMID 40356909, 2025). "Numerous studies show that specific RNA modification factors (such as METTL3, IGF2BP3, and ALKBH5) exhibit abnormal expression in various cancers." (PMID 40867324, 2025). "IGF2BP1, IGF2BP2, and IGF2BP3 were upregulated in the SCAN-B cohort, aligning with their widespread dysregulation in cancer." (PMID 40918643, 2025). "Mechanistically, we demonstrate that IGF2BP3 stabilizes the expression of OLFML1 to activate the Hedgehog signaling pathway, thereby promoting CRC cell proliferation and enhancing cancer stemness." (PMID 40765816, 2025). "Among them, IGF2BP3, notably abundant in pancreatic cancer tissues and initially named KOC, is particularly overexpressed in various human cancers." (PMID 40765570, 2025). "We analyzed the prognosis value of IGF2BP3 as well as the relationship between IGF2BP3 and immune checkpoints, immune cells, TMB, MSI, immunoinhibitors, immunostimulators, and MHCs in pan-cancer." (PMID 38577615, 2024). "Inhibition of IGF2BP3 expression by using JQ1 has the effect of slowing the growth and migration of cancer cells in Ewing sarcoma and improving poor prognosis." (PMID 39033180, 2024). "In conclusion, IGF2BP3 had a potential to be a new perspective biomarker in forecasting the immune response, ferroptosis, stemness and prognosis of HCC or even pan-cancer." (PMID 38577615, 2024). "More importantly, CDC25A expression was positively correlated with IGF2BP3 and METTL3 expression in most cancer types in TCGA datasets." (PMID 39247830, 2024). "Although IGF2BP3 has been discovered to exert cancer-promoting functions in HCC 15, 16, comprehensive bioinformatics analysis of IGF2BP3 in HCC and pan-cancer is scarce." (PMID 38577615, 2024). "Clinically, up-regulated IGF2BP3, METTL3, and CDC25A show a strong positive correlation in TCGA pan-cancer, including AEG." (PMID 39247830, 2024). "IGF2BP2, IGF2BP3, RBM15, WTAP, and YTHDC2 are positively correlated to the immune score in a few cancer types." (PMID 39457524, 2024). "For example, berberine inhibits IGF2BP3 expression, and hampers the normal process of the cell cycle by affecting the PI3K/AKT pathway, which in turn inhibits cancer cell proliferation in CRC." (PMID 39033180, 2024). "IHC results showed that METTL3, IGF2BP3, and CDC25A expression significantly increased in cancer tissues compared to normal adjacent tissues." (PMID 39247830, 2024). "In colon cancer, IGF2BP3 increases the stability of CCND1 mRNA and promotes the proliferation of cancer cells." (PMID 37340423, 2023). "In different cancer cell lines from the CCLE database, not only were IGF2BP3 expression levels significantly and generally elevated but smaller ranges were shown compared to the range of expression in normal human tissues." (PMID 36761737, 2023). "In the present study, aberrant IGF2BP3 expression was found to be correlated with TMB in 14 cancer types, and MSI in 10 cancer types." (PMID 36761737, 2023). "IGF2BP3 recognizes m6A‐modified MCM5 mRNA to promote their stability and upregulate MCM5 protein levels, leading to p‐EMT‐induced cancer cell plasticity." (PMID 37171793, 2023). "Thus, IGF2BP3 may have an important role within cancer stem cells that warrants further study." (PMID 37760460, 2023).
cancer (continued). "Compared with IGF2BP3, IGF2BP1 has a more complex role in cancer, possessing both pro- and anti-cancer effects, and therefore, IGF2BP3 correlates better with cancer progression., suggesting the importance of further studies on FOXM1 regulation of IGF2BP3." (PMID 37234166, 2023). "In short, IGF2BP3 plays an oncogenic role in stabilizing EGFR mRNA in an m6A-dependent manner and further regulates cancer cell proliferation and drug resistance to cetuximab in CRC cells." (PMID 37658049, 2023). "The RNA-binding protein, insulin-like growth factor 2 mRNA binding protein-3 (IGF2BP3), is overexpressed in a wide range of human cancers." (PMID 37760460, 2023). "With regard to cancer, an m6A score based on the expression of IGF2BP2, IGF2BP3, KIAA1429, METTL3, EIF3H, and LRPPRC was reported as an indicator of pancreatic tumor microenvironment status and was a potential biomarker for patients’ prognosis." (PMID 37903783, 2023). "Furthermore, we wondered whether IGF2BP3 played a critical role in cancer diagnosis and prognosis." (PMID 36761737, 2023). "Based on the bioinformatics above analysis, it is revealed that IGF2BP3 and AGAP2-AS1 are both highly expressed in both RCC cancer tissues and cells." (PMID 38110984, 2023). "Our data support IGF2BP3 mRNA quantification as a reliable prognostic marker for MSS and DMFS, as previously reported for other types of cancers." (PMID 35565448, 2022). "IGF2BP3, also known as IMP3, CT98, or VICKZ3, has been reported as a carcinogenic-related protein in many studies of diverse cancers." (PMID 35676262, 2022). "We believe that the cancer-promoting role of ECE2 gene is related to the modification of m6A, which may affect the methylation level of LUAD, especially HNRNPC, through its association with HNRNPC, IGF2BP1, IGF2BP3 or RBM15, and ultimately affect the progression of LUAD." (PMID 36299451, 2022). "To further understand the roles of YTHDF1, IGF2BP3 and NKAP in other cancers, we collected their expression levels from pan-cancer analysis." (PMID 35963644, 2022). "More importantly, YTHDF1, IGF2BP3 and NKAP were also highly expressed in pan-cancer, which provided the promise of YTHDF1, IGF2BP3 and NKAP as potential therapeutic targets." (PMID 35963644, 2022). "The data was obviously showed that YTHDF1, IGF2BP3 and NKAP were highly expressed in most cancer types." (PMID 35963644, 2022). "The result shown that the expression of both protein and RNA levels of IGF2BP2 and IGF2BP3 were up-regulated in COAD, ESCA, and STAD cancer tissues compared with paracancerous." (PMID 36686749, 2022). "We further summarized six genes (IGF2BP3, LYAR, RALY, STAU1, SYNCRIP, and TOP1) that displayed high correlations between mRNA and protein expression in both cancer and cell line databases." (PMID 36428700, 2022). "IGF2BP2 and IGF2BP3, members of the mammalian IGF2 mRNA-binding protein family, were found correlated with an overall poor prognosis and metastasis of various cancer." (PMID 34332578, 2021). "Collectively, the roles of DNAJC6, IGF2BP3, and ZC3H13 in regulating cancer progression as mentioned in above studies are consistent with our present study, indicating the results based on our study are reliable." (PMID 34312475, 2021). "Poor survival rates in patients were associated with the increased expression of these genes across cancer types, such as IGF2BP1 (HR = 1.324527, P = 2.38E-06) in LUAD and IGF2BP2 (HR = 1.198617, P = 0.006603) and IGF2BP3 (HR = 1.570331, P = 0.000198) in LIHC." (PMID 33519919, 2020). "Insulin-like growth factor 2 mRNA binding protein 3 (IGF2BP3/IMP3/KOC), initially identified as an RNA-binding protein, is highly expressed in embryonic tissues and a variety of cancers." (PMID 29212181, 2017). "The expression levels of CDH3, IGF2BP3, HOXB7, and BIRC5 mRNA in malignant biliary strictures were significantly higher than in benign strictures (P = 0.006, <0.001, <0.001, and 0.001, respectively)." (PMID 27399126, 2016).
cancer (continued). "Our data suggest that measuring IGF2BP3, HOXB7 and NEK2 mRNA levels by RT-PCR in addition to cytology has the potential to improve detection of malignant biliary disorders from brush cytology specimens." (PMID 22879911, 2012). "Moreover, significant positive correlations between VIRMA or IGF2BP3 protein expression and ANLN protein expression were observed in human pan-cancers." (PMID 41513610, 2026). "Despite the previously recognized impact of IGF2BP3 on cell proliferation and apoptosis in cancer cells, we did not observe significant effects on these processes upon modulating IGF2BP3 expression in MCC cells." (PMID 40162116, 2025). "IGF2BP3, an m6A “reader” regulating RNA metabolism, exhibits pan-cancer amplification, functions as a core RMS element, and critically influences GBM and multi-cancer prognosis." (PMID 40867324, 2025). "Our subgrouping analysis based on 25 m6A-associated genes revealed distinct m6A regulation-driven subgroups in six cancers, with IGF2BP family members (IGF2BP1, IGF2BP2, IGF2BP3; all known m6A readers) emerging as a central factor distinguishing these subgroups." (PMID 41049442, 2025). "Furthermore, IGF2BP3 has been shown to interact with various signaling pathways, including the PI3K and MAPK pathways, which are critical for cancer cell survival and proliferation." (PMID 40765570, 2025). "In addition, the IGF2BP3 and YTHDF1/eEF-2 complexes increase PDK4 mRNA stability through the m6A modification system, a process that promotes the glycolytic process of cancer cells and accelerates CC development." (PMID 40356909, 2025). "Additionally, IGF2BP3 modulates AS events, including those of PKM, contributing to metabolic reprogramming in cancer." (PMID 40563987, 2025). "Mechanistically, IGF2BP3 enhanced mRNA stability and promoted the expression of HMGB1 by binding to its mRNA, which is a factor that promotes inflammation and orchestrates tumorigenesis in many cancers." (PMID 38504159, 2024). "In this research, we mainly conducted a comprehensive analysis of IGF2BP3 in HCC and pan-cancer." (PMID 38577615, 2024). "IGF2BP3 has garnered significant attention due to its frequency of overexpression in many cancer types, lack of expression in normal adult tissues, and the association of expression levels with poor prognosis." (PMID 37760460, 2023). "Consequently, IGF2BPs possess significant cancer-promoting properties, with IGF2BP1 and IGF2BP3 abnormally re-expressed in malignancies considered bona fide oncofetal proteins." (PMID 37280679, 2023). "Thus, we evaluated the correlation between the IGF2BP3 gene expression and TMB and MSI in pan-cancer." (PMID 36761737, 2023). "This is akin to its role in mixed-lineage leukemia, wherein IGF2BP3 expression, induced by the MLL-AF4 leukemogenic pathway, positively regulates MLL-AF4 transcriptional targets, creating a feedforward process that drives cancer progression." (PMID 37760460, 2023). "Moreover, inhibiting the Notch signaling via NOTCH1 knockdown reversed IGF2BP3‐induced expression of genes related to p‐EMT and cancer cell plasticity." (PMID 37171793, 2023). "Second, there is no clinical trial to evaluate the use of IGF2BP3-related therapeutic drugs in patients with pan-cancer." (PMID 36761737, 2023). "Moreover, the relationship of IGF2BP3 expression with immune infiltrates, TMB, MSI and immune-related genes was evaluated in pan-cancer." (PMID 36761737, 2023). "IGF2BP3 is an RBP and exerts oncogenic function in cancers as a new m6A reader." (PMID 37877353, 2023). "IGF2BP1 and IGF2BP3 are re-expressed in many types of tumors, and IGF2BP2 was also found to be excessively expressed in malignancies due to genomic amplification according to pan-cancer analysis with TCGA data." (PMID 37644505, 2023).